CLPP (caseinolytic mitochondrial matrix peptidase proteolytic subunit)
Diseases named in the same sentence as CLPP in open-access papers (continued):
Sharing a sentence is not in itself a finding about the gene and the disease.
breast carcinoma (18 papers, 2020 to 2025). "In non-breast cancer settings, a high level of the c-myc protein is reported as a predictive biomarker for ClpP agonists in glioblastoma, and mutation of succinate dehydrogenase is proposed as a potential biomarker in neuroendocrine tumors." (PMID 37046596, 2023). "Knockdown of ClpP is associated with reduced proliferation, migration, and invasion of breast cancer cells." (PMID 36768800, 2023). "In addition, a high level of ClpP expression is associated with the disease stage, metastasis, poor prognosis and is proposed as a prognostic marker in breast cancers." (PMID 37046596, 2023). "In addition, ClpP regulates the proliferation and invasion of breast cancer cells via a mechanism associated with the Src/PI3K/AKT cascade." (PMID 35180892, 2022). "In addition, loss of ClpP suppresses cell growth, migration, and colony formation in the breast cancer cell lines MDA-MB-231 and ZR-75-1." (PMID 33922062, 2021). "In breast cancer, ClpP activation sensitizes cells to Tumor Necrosis Factor-Related Apoptosis-Inducing Ligand (TRAIL) and enhances apoptotic signaling, particularly in HER2+ subtypes." (PMID 41155556, 2025). "We then examine the status of the development of mitochondria-targeting drugs, with special highlight of the caseinolytic mitochondrial matrix peptidase proteolytic subunit (ClpP) as an emerging drug target in breast cancers." (PMID 37046596, 2023). "In contrast, activation of ClpP by ClpP agonists exerts an anti-tumor effect in breast cancer cells." (PMID 37046596, 2023). "Studies testing ONC201 and/or TR compounds in breast cancer models collectively show that ClpP agonists exert a significant anti-proliferative effect accompanied with ISR and cell cycle arrest, rather than inducing apoptosis." (PMID 37046596, 2023). "Recent studies revealed that the anti-proliferative effect of ClpP agonists observed in breast cancers represent a senescence-like phenotype." (PMID 37046596, 2023). "The unique characteristics and mechanism of action of ClpP agonists provide new opportunities in breast cancer treatment." (PMID 37046596, 2023). "We will then outline the status of the use of mitochondria-targeting drugs in breast cancers, and highlight ClpP agonists as emerging mitochondria-targeting drugs with a unique mechanism of action." (PMID 37046596, 2023). "For instance, in breast cancer, the CLPP chaperone realizes about 40% of its potential, while SPG7 realizes about 15%." (PMID 37805501, 2023). "Though ClpP agonists were found to inhibit cell proliferation in breast cancer and other cancer cell models, the anti-cancer mechanism of action is just beginning to be elucidated." (PMID 37371693, 2023). "Combination therapy with ClpP agonists is likely to be needed to improve the therapeutic efficacy in breast cancer." (PMID 37046596, 2023). "ClpP agonists recruit and activate NK cells in breast and other cancer models, and the cytotoxicity of ClpP-agonist was enhanced by NK cells in breast cancer cell line." (PMID 37046596, 2023). "ClpP agonists are promising new antitumor drugs in breast cancers worth further preclinical and clinical evaluations." (PMID 36388465, 2022). "Previous studies have shown that ClpP expression in primary samples from patients with various malignancies including breast cancers is increased compared with normal tissues." (PMID 36388465, 2022). "In this study, we report that ClpP agonists inhibit breast cancer cell proliferation and CSC function in vitro and in vivo." (PMID 36388465, 2022). "We previously reported that small molecule ONC201, which is an agonist for the mitochondrial caseinolytic protease (ClpP), induces mitochondrial dysfunction in breast cancer cells." (PMID 36388465, 2022). "In this study, we describe chemical optimization and characterization of the next generation of highly potent and selective small‐molecule ClpP activators (TR compounds) and demonstrate their efficacy against breast cancer models in vitro and in vivo." (PMID 35929764, 2022).
breast carcinoma (continued). "All ClpP agonists decreased cell viability in multiple breast cancer cells, including MB231 [triple-negative breast cancer (TNBC), basal B], MB453 (HER2-amplified), MCF7 (estrogen receptor positive)." (PMID 36388465, 2022). "Compounds tested for mitochondrial ClpP activation and binding, potent inhibition of breast cancer cell growth." (PMID 35929764, 2022). "In the current study, we further investigated the impact of ONC201 and the more potent TR ClpP agonists on breast cancer proliferation and CSC function." (PMID 36388465, 2022). "In conclusion, ClpP agonists inhibit breast CSC functions by disrupting mitochondrial homeostasis in breast cancer cells and inhibiting multiple pathways critical to CSC function." (PMID 36388465, 2022). "ClpP is overexpressed in breast cancer, providing the potential for utilizing highly selective and potent ClpP activators as a novel approach to disrupt mitochondrial metabolic processes required for TNBC proliferation." (PMID 35929764, 2022). "CLPP is also overexpressed in breast cancer, and CLPP depletion inhibits the SRC/PI3K/AKT pathway, which is crucial for cancer cell proliferation and invasion." (PMID 34361072, 2021). "According to The Cancer Genome Atlas (TCGA) database, ClpP is highly expressed in breast cancer tissue and is correlated with the T stage, ER expression, and lower recurrence-free survival." (PMID 33922062, 2021). "AML, acute lymphoblastic leukemia (ALL) and breast cancer cells with inactive mutant ClpP (D190A) or ClpP knockout are resistant to ONC201 and ONC212, indicating the functional importance of ClpP for imipridones efficacy." (PMID 33922062, 2021). "Recently, ClpP expression was measured in human breast cancer (BC) tissues and corresponding adjacent normal tissues, as well as in seven human BC cell lines and two normal mammary epithelial cell lines." (PMID 34207660, 2021). "ClpP emerges as a mitochondrial checkpoint with subtype-specific implications in breast cancer." (PMID 41155556, 2025). "In contrast, overexpression of ClpP increases migratory and invasive activity in breast cancer." (PMID 36768800, 2023). "Many preclinical studies have demonstrated the efficacy of ClpP agonists in breast cancer models." (PMID 37046596, 2023). "In breast cancer cells, transient knockdown of CLPP by siRNA induced apoptosis and inhibited cell viability, migration, invasion in breast cancer cells, while CRISPR/Cas9-mediated deletion of CLPP gene did not affect cell viability presumably due to cellular adaptation." (PMID 37046596, 2023). "The combination of ClpP agonists with ICIs needs to be explored in breast cancers." (PMID 37046596, 2023). "ClpP is upregulated in breast cancer, PCa, and acute myeloid leukemia." (PMID 35864539, 2022). "Conversely, overexpression of ClpP increases migratory and invasive activity in breast cancer." (PMID 35864539, 2022). "In this study, we examined the effect of ClpP agonists on CSC function in breast cancer." (PMID 36388465, 2022). "High ClpP expression correlates with poor recurrence-free survival in breast cancer." (PMID 35864539, 2022). "Thus, ClpP is considered an emerging target for breast cancer." (PMID 37046596, 2023). "Further, in human breast cancer SUM159 cells, D9 activates ClpP, promoting the degradation of mitochondrial transcription factor A (TFAM) and mitochondrial Tu translation elongation factor (TuFM)." (PMID 40395852, 2025). "In breast cancer, silencing ClpP decreases the activity of SRC and AKT and phosphorylation of PI3K, thereby interfering with the proliferation, migration and apoptosis of breast cancer cells." (PMID 39261452, 2024). "Among multiple ClpP agonists, ONC201 is the only ClpP agonist entered in clinical trials for breast cancers as of January 2023." (PMID 37046596, 2023). "Among ClpP agonists, ONC201 has been most extensively tested in various preclinical models, including breast cancers." (PMID 37046596, 2023).
breast carcinoma (continued). "Knockdown of ClpP by SiRNA decreased the response to ONC201 and blocked the expression of CHOP and the cytostatic effects induced by ONC201 in breast cancer cells." (PMID 35372029, 2022). "Several studies have proven that high levels of ClpP and LONP1 in colorectal cancer, prostate cancer, breast cancer and melanoma are notably correlated with poor prognosis in cancer patients." (PMID 35180892, 2022). "We report that ClpP agonists inhibit cell growth and CSC functions in breast cancer models by modulating multiple metabolic pathways essential to CSC function." (PMID 36388465, 2022). "Our bioinformatic analysis of the cancer genome atlas breast cancer (TCGA-BRCA) dataset found that the transcript level of CLPP is significantly higher in TNBC and basal breast cancer subtypes compared with other subtypes." (PMID 36388465, 2022). "In MCF-7 tumor cell lines of human breast cancer, however, the proliferation of tumor cells is not affected by the downregulation of ClpP expression." (PMID 40395852, 2025). "While the exact roles of ClpP in tumorigenesis are not clearly established, emerging evidence demonstrate that ClpP is overexpressed in multiple malignancies including breast cancers." (PMID 37046596, 2023). "Since ClpP activators, but not ClpP inhibitors, show cytotoxicity in breast cancers, we will focus on ClpP activators in this review (for ClpP inhibitors, we refer readers to other excellent reviews." (PMID 37046596, 2023). "This suggests that ClpP activation, but not ClpP inhibition, is the better targeting approach in breast cancers." (PMID 37046596, 2023). "ClpP agonists have been actively exploited in multiple clinical trials with various types of malignancies; however, clinical studies of ClpP agonists in breast cancers have not reported results." (PMID 37046596, 2023). "ClpP agonist-induced mitochondrial dysfunction effectively halts cell growth and induces senescence, but not apoptosis in breast cancers." (PMID 37046596, 2023). "Hyperactivating ClpP induces uncontrolled, but selective, degradation of ClpP substrates and disrupts mitochondrial functions, leading to growth inhibition of breast cancer cells, without adverse effect in non-malignant cells." (PMID 37046596, 2023). "We tested multiple ClpP agonists (ONC201, TR-57, TR-65) in breast cancer cell lines." (PMID 36388465, 2022). "While the mechanisms of the interaction between ClpP and the mitochondrial mechanics remain to be investigated, ClpP inactivation has made tumor cells at least partially resistant to ONC201 in AML, acute lymphoblastic leukemia (ALL) and breast cancer cells." (PMID 34531756, 2021). "However, the expression pattern and biological functions of ClpP in breast cancer (BC) have not yet been investigated." (PMID 32195060, 2020).
Perrault syndrome type 3 (11 papers, 2015 to 2025). "Exome analysis identified a novel missense mutation in the CLPP gene in a consanguineous Saudi family expanding the clinical spectrum of Perrault Syndrome type 3." (PMID 38002872, 2023). "The mutations in CLPP lead to the development of Perrault syndrome type 3, in which the main clinical manifestations are ovarian insufficiency and varying degrees of hearing loss." (PMID 37007963, 2023). "Defects in CLPP cause Perrault syndrome type 3 (PRLTS 3), with clinical manifestations of sensorineural deafness and POI." (PMID 37007963, 2023). "In the human organism, mutations in the mitochondrial matrix peptidase ClpP lead to Perrault syndrome type 3 (PRLTS3)." (PMID 34345994, 2021). "Loss-of-function mutations in the human ClpP gene, which is mainly responsible for mitoribosome folding quality, lead to an autosomal recessively inherited disease called Perrault syndrome type 3 (PRLTS3)." (PMID 32342250, 2020). "Alternatively, CLPP mutations are associated with Perrault syndrome type 3 (PRLTS3, MIM #614129), an autosomal recessive disorder characterised by sensorineural hearing loss and premature ovarian failure following ovarian dysgenesis, with variable neuropathies." (PMID 40857737, 2025). "Biallelic pathogenic variants in CLPP, encoding mitochondrial matrix peptidase ClpP, cause a rare autosomal recessive condition, Perrault syndrome type 3 (PRLTS3)." (PMID 34943861, 2021). "Perrault syndrome type 3 (PRLTS3) is caused by mutations in CLPP, and to date seven different mutations have been identified in patients." (PMID 30150665, 2018).
ovarian failure (9 papers, 2015 to 2025). "Importantly, only CLPP mutations are responsible for the autosomal recessive combination of ovarian failure with sensorineural deafness, whose underlying mitochondrial causes usually affect the mtDNA/mtRNA processing protein complexes." (PMID 35954215, 2022). "This study identified a novel CLPP missense variant (c.628G > A) in a woman with POI who presented with secondary amenorrhea, ovarian dysfunction, and primary infertility." (PMID 37007963, 2023).
leukemia (8 papers, 2016 to 2025). A malignant (clonal) hematologic disorder, involving hematopoietic stem cells and characterized by the presence of primitive or atypical myeloid or lymphoid cells in the bone marrow and the blood. "This review highlighted the relevance of ClpP in a broad spectrum of cancers, including leukemia, gliomas, colorectal, breast, prostate, pancreatic, ovarian, and liver tumors." (PMID 41155556, 2025). "CLPP is an essential gene for cell survival in leukemia cells and ClpP inhibition is lethal in acute myelogenous leukemia (AML), chronic myelogenous leukemia, and osteosarcoma." (PMID 37046596, 2023). "By targeting the mitochondrial protease ClpP with a beta-lactone inhibitor called A2-32-01, Cole and colleagues demonstrated that this compound was effective at killing leukemia cells with high levels of ClpP expression." (PMID 33883040, 2021). "ClpP hyperactivation induces apoptosis in leukemia and lymphoma cells preferentially over normal cells." (PMID 33922062, 2021). "Genetic and chemical inhibition of ClpP reduces leukemia cell growth and viability and targets leukemic stem cells in vitro and in vivo." (PMID 33922062, 2021). "Therefore, the protein expression of the ClpX chaperone and ClpP were assessed in different leukemia cell lines." (PMID 34045646, 2021).
glioma (7 papers, 2021 to 2025). A benign or malignant brain and spinal cord tumor that arises from glial cells (astrocytes, oligodendrocytes, ependymal cells). "Overall, ClpP is a key vulnerability in high-grade gliomas, linking mitochondrial metabolism, oxidative stress, and epigenetic control." (PMID 41155556, 2025). "As ClpP is overexpressed across diffuse gliomas at an mRNA and protein level, the therapeutic potential of imipridones in glioma remains incredibly promising." (PMID 41008904, 2025). "ONC201, a dopamine receptor D2 (DRD2) antagonist and caseinolytic protease P (ClpP) agonist, has induced durable tumor regressions in adults with recurrent H3 K27M-mutant glioma." (PMID 36382108, 2022). "Given the central role of mitochondria in the survival and therapy resistance of gliomas such as diffuse midline gliomas (DMGs), targeting ClpP may offer a realistic therapeutic avenue." (PMID 41155556, 2025). "Finally, we provide a summary of mitochondrial targeting efforts, including a therapeutic breakthrough through ClpP agonism, and touch on crosstalk between mitochondrial metabolism and epigenetics that may be exploitable for glioma treatment." (PMID 41008904, 2025). "ClpP agonists induce senescence in TNBC cells, whereas apoptosis is more common in other cancers, such as H3K27 mutant gliomas targeted by ONC201." (PMID 41333384, 2025). "ClpP has emerged as a promising anticancer target following the discovery of ONC201, actually approved FDA to treat high grade glioma, and related small-molecule activators." (PMID 41155556, 2025). "Interestingly, combining ClpP agonists with epigenetic therapies, such as HDAC or EZH1/2 inhibitors, has also been shown to enhance antitumor efficacy in high-grade gliomas." (PMID 41008904, 2025).
deafness (6 papers, 2017 to 2024). An inherited or acquired condition characterized by the complete loss of the ability to hear from one or both ears. "These DNAJA3 anomalies are followed by early-onset deafness in ClpP-mutant patients, while a recent report showed anomalies of the mitochondrial matrix chaperone DNAJC30 to occur in hereditary optic nerve atrophy." (PMID 34345994, 2021). "Similarly to mutations in CLPP, mutations in PNPT1 are also the cause of progressive deafness and of a sensory neuropathy with ataxia." (PMID 38927630, 2024).
hearing loss (6 papers, 2020 to 2025). "Thus, the screening for the genetic variants of CLPP may be clinically relevant in patients with unexplained gonadal dysfunction or hearing impairment." (PMID 37007963, 2023).
prostate carcinoma (6 papers, 2016 to 2025). A carcinoma that arises from epithelial cells of the prostate gland. "RNA expression of both LONP1 and ClpP were significantly upregulated in a wide range of human cancers, including bladder, breast, colon, kidney, lung, thyroid, uterine, and prostate cancer, compared with normal tissue." (PMID 33637676, 2021). "Separate knockdown of LONP1 or ClpP genes with small interfering RNA (siRNA) reduced the growth of prostate cancer cells, including LNCaP, C4-2B, DU145, and PC3 cells." (PMID 33637676, 2021). "siRNA silencing of ClpP or ClpX resulted in increased total cellular superoxide production in prostate cancer cells." (PMID 27389535, 2016). "In contrast, knockdown of ClpX or ClpP significantly reduced Complex II activity in PC3 cells as well as other prostate cancer cell types, including C4-2 and DU145." (PMID 27389535, 2016). "Interestingly, LONP1 and ClpP genes closely localized to chromosomal region 19 (19q13), and the genomic locus of these two genes frequently exhibited gain in prostate cancer patient samples." (PMID 33637676, 2021). "To assess whether co-expression of these two proteases plays a role in cancer, we examined whether LONP1 and ClpP downregulation jointly impact the proliferation of prostate cancer cells." (PMID 33637676, 2021). "Consistently, prostate cancer patients with high levels of both LONP1 and ClpP expression showed significantly worse survival outcomes than those with only high LONP1 or ClpP expression." (PMID 33637676, 2021). "Additionally, prostate cancer patients with higher LONP1 and ClpP expression exhibited poorer survival." (PMID 33637676, 2021). "In agreement with mRNA data, LONP1 and ClpP proteins were highly co-expressed in prostate cancer compared with non-transformed prostate cells, including RWPE1 and BPH1 cells." (PMID 33637676, 2021). "In addition, in the Cancer Cell Line Encyclopedia (CCLE) database containing 1457 cancer cell lines, median ClpP expression was the highest in prostate cancer, and LONP1 expression was also highly elevated in prostate cancer relative to other cancer types." (PMID 33637676, 2021).
Ataxia (5 papers, 2019 to 2025). Ataxia refers to impaired coordination of voluntary muscle movement. "Therefore, the late-onset progressive neuropathy, ataxia, and leukodystrophy in patients with ClpP mutations might be mediated by innate immune activation." (PMID 34345994, 2021). "Furthermore, the novel enrichment of neurodegeneration networks among DNAJA3 is compatible with the idea that the ataxia and neuropathy of ClpP-mutant patients are modulated by DNAJA3 accumulation." (PMID 34345994, 2021).